ZC3H11A (zinc finger CCCH-type containing 11A)
Description:
Through its association with TREX complex components, may participate in the export and post-transcriptional coordination of selected mRNA transcripts, including those required to maintain the metabolic processes in embryonic cells. Binds RNA. (Microbial infection) Plays a role in efficient growth of several nuclear-replicating viruses such as HIV-1, influenza virus or herpes simplex virus 1/HHV-1. Required for efficient viral mRNA export. May be required for proper polyadenylation of adenovirus type 5/HAdV-5 capsid mRNA.
Synonyms: KIAA0663; ZC3HDC11A
Tractability: PROTAC: UniProt records ubiquitination sites on it; ubiquitination databases record sites on it; its protein half-life has been measured.
Gene: Protein-coding gene on chromosome 1 (203,795,623 to 203,854,999, forward strand). Ensembl gene ENSG00000058673.
Subcellular location: Nucleus; Nucleus speckle
Subcellular location (Human Protein Atlas): Nuclear speckles
Pathways (Reactome):
Metabolism of RNA: Transport of Mature mRNA derived from an Intron-Containing Transcript; mRNA 3'-end processing
Gene Ontology:
Molecular function: protein binding; RNA binding; metal ion binding
Biological process: poly(A)+ mRNA export from nucleus; mRNA export from nucleus
Cellular component: nuclear speck; nucleus; transcription export complex; nucleoplasm
Genetic constraint (gnomAD): Loss-of-function variants: 17 observed, 88.9 expected, observed/expected ratio (o/e) 0.19, 90% interval 0.13 to 0.29. The upper end of that interval is the gene's LOEUF score, 0.29, which puts it in group 1 of 6, group 1 being the genes least tolerant of losing a copy. Missense variants: 695 observed, 972.65 expected, observed/expected ratio (o/e) 0.71, 90% interval 0.67 to 0.76. Synonymous variants: 292 observed, 347.79 expected, observed/expected ratio (o/e) 0.84, 90% interval 0.76 to 0.93.
Homologues: Orthologues: chimpanzee ZC3H11A (99% identical), macaque ZC3H11A (98% identical), dog ZC3H11A (89% identical), mouse Zc3h11a (79% identical), tropical clawed frog zc3h11a (40% identical), zebrafish zc3h11a (36% identical). Paralogues in human: ZC3H11C (93% identical), ZC3H11B (93% identical), ZC3H11D (11% identical).
Diseases named in the same sentence as ZC3H11A in open-access papers:
ZC3H11A is named in the same sentence as 14 diseases in open-access papers, as found by Europe PMC text mining. Sharing a sentence is not in itself a finding about the gene and the disease. The quoted sentences say what the papers report.
myopia (3 papers, 2012 to 2025). "Fourth, changes in Zc3h11a expression were found to cause changes in the myopia-related genes Tgfβ1, Mmp2, and Il6." (PMID 40864167, 2025). "Although the function of the ZC3H11B in humans is presently unknown, the implicated role of the murine gene ZC3H11A (conserved gene of ZC3H11B in mouse) in myopia development is in keeping with previous findings that several zinc finger proteins are involved in myopia." (PMID 22685421, 2012). "Zc3h11a expression has been shown to be altered in the murine retina and sclera in an experimental myopia mouse model." (PMID 36207342, 2022). "In addition, the expression levels of myopia-related factors, such as Tgfβ1, Mmp2, and Il6, were upregulated in the retina and sclera of the Zc3h11a+/- mice." (PMID 40864167, 2025). "The Zc3h11a+/- mice exhibited significant shifts in refraction toward myopia." (PMID 40864167, 2025). "However, the precise pathological mechanism of ZC3H11A in myopia development remains unclear, necessitating further research." (PMID 40864167, 2025). "In light of this, the observation that ZC3H11B is abundantly expressed in retina and sclera, together with the significant down-regulation of the coding counterpart ZC3H11A in myopic mice eyes, suggests it may promote or inhibit the transcription of ocular growth genes vital in myopia development." (PMID 22685421, 2012). "Proteomic studies further suggest ZC3H11A involvement in the TREX complex, implicating RNA export mechanisms in myopia pathogenesis." (PMID 40864167, 2025). "In addition, variations in the expression of murine gene ZC3H11A and two neighboring genes SLC30A10 and LYPLAL1 in the retina and sclera in a myopic mouse model implicate the role of these genes in myopia onset." (PMID 22685421, 2012). "Thus, Zc3h11a may exert an influence on PI3K-AKT and NF-κB signaling pathways by modulating the cytoplasmic levels of IκBα, contributing to the development of myopia." (PMID 40864167, 2025).
lung adenocarcinoma (2 papers, 2018 to 2024). A carcinoma that arises from the lung and is characterized by the presence of malignant glandular epithelial cells. "Interestingly, ZC3H11A overexpression correlates with the occurrence of KRAS mutations in lung adenocarcinoma, providing a link between the Ras/MAPK pathway and ZC3H11A." (PMID 38342435, 2024). "We identified three genes (GATAD2B, ACVR1B, and ZC3H11A) whose overexpression significantly correlates with mutant KRAS lung adenocarcinoma vs wild-type KRAS status in patients." (PMID 30013058, 2018).
viral infections (2 papers, 2022 to 2024). "ZC3H11A has been identified as a stress-induced protein that is highly upregulated in stress conditions such as virus infection and heat shock." (PMID 39582529, 2024). "Zinc finger CCCH containing 11A (ZC3H11A) is a stress-induced protein that is upregulated in various conditions such as heat shock and virus infection." (PMID 39582529, 2024). "ZC3H11A is a stress-induced protein that plays an important role in regulating the nuclear mRNA export under situations of stress, such as heat-shock and viral infections." (PMID 36439101, 2022).
amyotrophic lateral sclerosis (1 paper, 2020). Amyotrophic lateral sclerosis (ALS) is a neurodegenerative disease characterized by progressive muscular paralysis reflecting degeneration of motor neurons in the primary motor cortex, corticospinal tracts, brainstem and spinal cord. "Further, it has been reported that ZC3H11A associates with a mutant version of the nuclear matrix protein, Matrin-3, which has been found in patients with amyotrophic lateral sclerosis (ALS)." (PMID 33217981, 2020).
cervical carcinoma (1 paper, 2021). A carcinoma arising from either the exocervical squamous epithelium or the endocervical glandular epithelium. "The increased sample size enabled identification of SMGs previously unreported in cervical carcinoma including NBPF10 (8%), RANBP2 (6%), MSN (6%), KRT8 (6%), POTEC (6%), ZC3H11A (4%), BMS1 (4%), GPX1 (3%), OTOP1 (3%), DNAH12 (2%), COIL (2%), TBC1D26 (2%), SPRED3 (2%), FAM115A (2%), and ARIH1 (1%)." (PMID 34620846, 2021).
colorectal carcinoma (1 paper, 2024). A malignant epithelial neoplasm that arises from the colon or rectum and invades through the muscularis mucosa into the submucosa. "As such, ZC3H11A may contribute to the development of different types of cancer (including colorectal carcinoma) by participating in mRNA processing and nuclear exporting processes, which are critical for tumor progression." (PMID 39582529, 2024). "Our study aimed to investigate the impact of inhibiting the ZC3H11A gene in cancer, particularly melanoma and colorectal carcinoma, using ASO as a tool to evaluate ZC3H11A function and evaluate ZC3H11A ASOs as a potential therapeutic agent." (PMID 39582529, 2024).
glioma (1 paper, 2023). A benign or malignant brain and spinal cord tumor that arises from glial cells (astrocytes, oligodendrocytes, ependymal cells). "In the present study, by transcriptomic sequencing and cell line validation, one of the genes that have been shown to be significantly affected by HCMV infection in gliomas is ZC3H11A (ZC3)." (PMID 38033582, 2023).
HCMV infection (1 paper, 2023). "Here we discovered a stress-induced nuclear protein ZC3H11A (ZC3) through high-throughput sequencing after HCMV infection, which has been reported recently by our research group in regulating mRNA export under stress conditions." (PMID 38033582, 2023). "Interestingly, HCMV infection also resulted in a significant increase in the ZC3H11A protein at late time points of infection." (PMID 38033582, 2023).
lower respiratory tract infections (1 paper, 2022). "A previous study demonstrated that host transcriptome profiles helped build a host transcriptional classifier (NFAT-5, ZC3H11A, and PRRC2C) for diagnosing lower respiratory tract infections with an AUC of 0.88 (95% CI, 0.75-1.00)." (PMID 36483456, 2022).
melanoma (1 paper, 2024). A malignant, usually aggressive tumor composed of atypical, neoplastic melanocytes. "We conducted NanoString RNA profiling of B16 melanoma cells that were transfected with ASO-ZC3_1 to determine the impact of ZC3H11A knockdown on pathway activity." (PMID 39582529, 2024). "An ASO targeting ZC3H11A was validated and evaluated in vitro and in the B16 melanoma model in vivo." (PMID 39582529, 2024). "Treatment with the ZC3H11A-targeted ASO had limited efficacy in vivo, while constitutive lentiviral shRNA knockdown of ZC3H11A in murine B16 melanoma cells and human HeLa cells led to reduced tumor growth with prolonged survival of mice, validating ZC3H11A as a relevant target for cancer therapy." (PMID 39582529, 2024). "Moreover, in a melanoma study, it was found that the overexpression of ZC3H11A, CEP170, and NUCKS1 work collectively as competitive endogenous RNA to sequester microRNAs that potentially have a suppressive role in cancer progression and metastasis." (PMID 39582529, 2024).
cancer (3 papers, 2019 to 2024). A tumor composed of atypical neoplastic, often pleomorphic cells that invade other tissues. "According to a recent report, ZC3H11A may be upregulated in cancer cells and may be associated with poor overall survival." (PMID 39582529, 2024). "Yu and colleagues showed that targeting the stress-induced zinc finger protein ZC3H11A can be a potential cancer therapy." (PMID 39582529, 2024). "Collectively, these data strongly suggested that ZC3H11A is a valid target for cancer immunotherapy." (PMID 39582529, 2024). "Taken together, these data strongly suggest that ZC3H11A is a valid target for cancer therapy, but the effective targeting of ZC3H11A poses a significant challenge." (PMID 39582529, 2024). "This project investigated the impact of ZC3H11A knockdown on cancer pathways and explored its potential as a target for cancer therapy." (PMID 39582529, 2024). "The aim of this study was to evaluate the feasibility of targeting ZC3H11A as a therapeutic approach for cancer treatment, using nuclease-resistant, affinity-enhanced antisense oligonucleotide (ASO)." (PMID 39582529, 2024). "In the context of cancer, several studies have reported high levels of ZC3H11A in cancer tissues compared to normal tissues." (PMID 39582529, 2024). "Furthermore, we identified a set of genes exhibiting analogous expression patterns to ZC3H11A in TCGA pan-cancer cohorts, implying a potential functional role for ZC3H11A in mRNA processing." (PMID 38033582, 2023). "The authors utilized antisense oligonucleotides to knock down ZC3H11A in different cancer models and observed increased interferon response, antigen presentation, and immunogenic apoptosis, which are collectively crucial for boosting the immune response against cancer." (PMID 39582529, 2024). "Apart from the four genes, other genes such as FBXL19, CSTF2, ZC3H11A, CRTC1 and MAGI3 influenced the formation and progression of human cancers with either carcinogenic or tumor-suppressive function." (PMID 30640723, 2019).
infection (3 papers, 2022 to 2023). The state of being infected such as from the introduction of a foreign agent such as serum, vaccine, antigenic substance or organism. "Briefly explaining, figuratively, the initiation of infection with SARS-CoV-2 using ACE2 as a receptor for viral entry and infectivity is augmented by ZFPs like ZDHHC18, ZNF267, and ZC3H11A (seen in Omicron infection)." (PMID 38025778, 2023). "This indicates that NF-κB signaling, which is upregulated at a very early time of infection in ZC3-KO cells, cannot be efficiently blocked in the absence of the ZC3H11A protein." (PMID 36439101, 2022).
tumor (2 papers, 2019 to 2024). "To confirm whether ZC3H11A is a viable therapeutic target, we further evaluated tumor growth and survival after subcutaneous injection of the B16 stable cell line with permanent knockdown of ZC3H11A." (PMID 39582529, 2024). "ZBED6 is not affected in the CRISPR KO cell line, and the delayed tumor growth of HeLa-KO-ZC3 is a strong indication that specific targeting of ZC3H11A can result in a therapeutic effect." (PMID 39582529, 2024). "However, stable knockdown of ZC3H11A led to upregulated MHC class I expression, increased cytotoxic CD8+ cell infiltration, and altered tumor microenvironment." (PMID 39582529, 2024).
ZC3H11A also shares sentences with these, for which no sentence is quoted: adenovirus infection (1 paper).